GATA6 (GATA binding protein 6)
Diseases named in the same sentence as GATA6 in open-access papers (continued):
Sharing a sentence is not in itself a finding about the gene and the disease.
Pallister Killian syndrome (1 paper, 2014). "Among the differentially expressed genes, we identified several genes whose misexpression may be associated with the clinical phenotype of Pallister Killian syndrome such as downregulation of ZFPM2, GATA6 and SOX9, and overexpression of IGFBP2." (PMID 25329894, 2014).
papilloma (1 paper, 2019). A benign epithelial neoplasm that projects above the surrounding epithelial surface and consists of villous or arborescent outgrowths of fibrovascular stroma. "In addition to increasing the overall number of tumors per mouse, loss of Gata6 led to an increase in papilloma‐like tumors and a decrease in tumors with SG elements." (PMID 30886049, 2019). "Gata6 was expressed in all K14ΔNLef1 tumors, whereas it was undetectable in DMBA/TPA‐induced papillomas in WT mice." (PMID 30886049, 2019).
peritoneal adhesions (1 paper, 2023). "GATA6+ macrophages, located in the peritoneal cavity, could rapidly aggregate to seal injuries and promote the repair of focal lesions, but they also formed extensive aggregates to promote the growth of intra‐abdominal tissue known as peritoneal adhesions in iatrogenic surgical situations." (PMID 37519221, 2023).
preeclampsia (1 paper, 2024). Preeclampsia is a hypertensive disorder of pregnancy that is characterized by new-onset hypertension with proteinuria presenting after 20 weeks of gestation, and depending on mild or severe forms may initially present with severe headache, visual disturbances, and hyperreflexia. "The reduction in GATA6 expression that appeared specific to preeclampsia provides a novel finding, as it has yet to be explored in the placenta or in pregnancy." (PMID 39028417, 2024). "Observed reductions to GATA6 expression in preeclampsia and enrichment in trophoblasts committed to an EVT cell fate may therefore indicate aberrations in trophoblast specification." (PMID 39028417, 2024). "GATA6 was downregulated in preeclampsia (p = 0.0014) and FGR (p = 0.0146)." (PMID 39028417, 2024).
prostate tumors (1 paper, 2024). "Conversely, GATA5 and GATA6 gene expression were negatively correlated with DNA methylation at specific loci in prostate tumors and adjacent non-tumor tissues regardless of race (left panel: left bottom quadrant)." (PMID 38566104, 2024).
psoriasis (1 paper, 2021). An autoimmune condition characterized by red, well-delineated plaques with silvery scales that are usually on the extensor surfaces and scalp. "Several psoriasis-related genes were among the associated genes of hsa_skin_088763, including GATA6, SIK2, IL17RD, EGR3, FAS, LRIG1, and PPARGC1A." (PMID 34068434, 2021). "Psoriasis-related gene GATA6 was an associated gene of hsa_skin_052271." (PMID 34068434, 2021). "Among the associated genes were EGR3, GATA6, GATA3, and FOXN3, which play important roles in psoriasis." (PMID 34068434, 2021).
Pulmonary valve atresia (1 paper, 2025). A congenital disorder of the pulmonary valve in which the orifice of the valve fails to develop. "Severe autosomal dominant CHDs such as complex right-sided anomalies including RV hypoplasia, TOF, and pulmonary valve atresia are also linked to missense variants in the GATA6." (PMID 40076735, 2025).
renal cell cancer (1 paper, 2015). "Moreover, recent profile studies showed that miR-506 regulated the biological behavior of cancer cells by targeting FLOT1 and GATA6 in renal cell cancer and oral squamous cell cancer." (PMID 26452129, 2015).
salivary gland adenoid cystic carcinoma (1 paper, 2021). An adenoid cystic carcinoma arising from the salivary gland. "Subsequently, we used reverse transcription-polymerase chain reaction RT-PCR and Western blot methods to detect the mRNA and the protein expressions of GATA6 in normal oral epithelial cells, human tongue squamous cell carcinoma cells, and human salivary gland adenoid cystic carcinoma cells." (PMID 34006300, 2021).
sebaceous carcinomas (1 paper, 2019). "However, sebaceous carcinoma can also acquire Gata6 mutations correlating with the total mutational burden." (PMID 30886049, 2019). "The percentage of Gata6‐positive cells was typically in the same range within each tumor group, except in the case of sebaceous carcinomas, which exhibited more variability in Gata6 expression." (PMID 30886049, 2019).
Sepsis (1 paper, 2021). Sepsis is defined as life-threatening organ dysfunction caused by a dysregulated host response to infection. "In PCV, we found that transcription factors such as Cebpb, Gata6 and several miRs such as miR-4769-3p, miR-362-5p, miR-510, might regulate most DEGs of PCV during sepsis." (PMID 34638535, 2021).
serous ovarian cancer (1 paper, 2009). "GATA4 expression is absent in the majority of serous ovarian cancer, and GATA6 is also absent in many but also positive in some cases." (PMID 19649254, 2009).
teratocarcinoma (1 paper, 2010). A germ cell tumor characterized by the presence of an embryonal carcinoma component and a teratoma component. "Although, it is unknown how RA signals stimulate GATA4/6 expression in this system, previous studies of pluripotent F9 teratocarcinoma cells have identified GATA4 and GATA6 as transcriptional targets of RARγ and RARβ2 signaling complexes, respectively." (PMID 20644631, 2010).
teratoma (1 paper, 2012). A non-seminomatous germ cell tumor characterized by the presence of various tissues which correspond to the different germinal layers (endoderm, mesoderm, and ectoderm). "We did find that the expression of Pax6 and Sox17 (except in GATA6) was lower than ES-EB, even though all of the selected iPSC lines in our study can generate teratoma, a gold standard of pluripotency." (PMID 22529890, 2012).
Truncus arteriosus (1 paper, 2019). A single arterial trunk arises from the cardiac mass. "Gata4/Gata6 compound heterozygotes displayed persistent truncus arteriosus (PTA), a severe OFT defect caused by combined alignment and OFT septation defects." (PMID 31120883, 2019).
ulcerative colitis (1 paper, 2024). An inflammatory bowel disease involving the mucosal surface of the large intestine and rectum. "Interestingly, our results are consistent with the increased HBD2 mRNA expression and HBD2 peptide production measured in biopsies from ulcerative colitis patients, an IBD in which GATA6 expression may be decreased." (PMID 38965312, 2024).
tumor (147 papers, 2008 to 2026). "This organoid library was used to identify the nongenetic mechanisms of niche independence, revealing its association with GATA6‐mediated transcriptional subtypes and tumor progression through genetic perturbation and CRISPR–Cas9 editing." (PMID 41503026, 2026). "On the other hand, our finding of increased GATA6 in DGC (the subset with better outcomes) aligns with evidence that loss of GATA6 activity is associated with tumor progression." (PMID 40862793, 2025). "GATA6 regulated tumor cell plasticity and immune evasion and its loss induced a basal transcriptional program driven by ΔNp63." (PMID 40699746, 2025). "The association between high GATA6 IHC and an anti-tumor immune environment offers a promising avenue for developing personalized immune therapies to enhance patient outcomes." (PMID 38733987, 2024). "Altered expression of GATA4, GATA5, and GATA6 are associated with abroad range of tumours emerging from the gastrointestinal tract, lungs and brain." (PMID 35488350, 2022). "Our data suggest a p300/GATA6 differentiation axis, where loss of this axis leads to tumor dedifferentiation." (PMID 35536676, 2022). "In this case, GATA6 can indirectly prevent cetuximab resistance caused by enhanced Wnt signaling to exert a tumor suppressor effect, which is different from previous studies in that GATA6 promotes tumorigenesis by activating Wnt signaling." (PMID 36212400, 2022). "We questioned if autophagy deficiency downregulated GATA6 expression in Tim-4+ TAMs and affected their development in tumor." (PMID 32780724, 2020). "We conclude that inhibition of GATA6 causes compensatory reprogramming and activation of chromatin at distal enhancers linked to the expression of known lineage-specific tumor suppressive genes." (PMID 32157212, 2020). "We extend prior data indicating GATA6 as a hallmark of tumour differentiation, provide strong evidence that it regulates the epithelial phenotype through novel mechanisms and show its potential as a marker for patient stratification." (PMID 27325420, 2017). "GATA6 is lost in tumours, in association with altered differentiation and the acquisition of a basal-like molecular phenotype, consistent with an epithelial-to-epithelial (ET2) transition." (PMID 27325420, 2017). "GATA6 is amplified in a subset of tumours and was proposed to be oncogenic, but high GATA6 levels are found in well-differentiated tumours and are associated with better patient outcome." (PMID 27325420, 2017). "E-cadherin was consistently low/mislocalised in all the GATA6neg tumours and in areas of focal GATA6 loss." (PMID 27325420, 2017). "In physiological conditions, it mediates acinar cell maintenance, whereas a loss of Gata6 in pancreatic carcinogenesis was associated with late and poorly differentiated tumor stages." (PMID 26716510, 2016). "The QM-PDA category demonstrated an association with elevated tumor grade and unfavorable survival outcomes, while the classical subtype exhibited the presence of the endodermal lineage-specifying transcription factor GATA6 and showcased dependency on KRAS." (PMID 39717718, 2025). "Computer assistance also improved the association between GATA6 IHC expression and tumor size change in patients receiving first-line mFFX (P = 0.015 vs. P = 0.20 for pathologist 1; P = 0.015 vs. P = 0.19 for pathologist 2, with and without computer assistance respectively)." (PMID 34294813, 2021). "Moreover, we confirmed the in vivo TSG function of GATA6 and confirmed that restoration of GATA6 expression slows down the growth of established xenografted tumor nodules deficient in GATA6 function." (PMID 32596145, 2020). "Interestingly, the reciprocal loss of GATA4 or GATA6 in epithelium-derived tumor cells reveals a subsequent loss of Laminin expression." (PMID 31685844, 2019). "In addition, correlation analysis showed that low-level GATA6 expression in GC tissues was significantly associated with a more aggressive tumor phenotype." (PMID 30674866, 2019).
tumor (continued). "Since loss of Gata6 in cultured mouse keratinocytes leads to DNA damage, triggering apoptosis, we investigated whether the tumor suppressive function of Gata6 might be due to an effect on MMR gene transcription." (PMID 30886049, 2019). "By contrast, GATA6 has been implicated as a tumor suppressor gene in astrocytomas." (PMID 21811562, 2011). "The enhanced GATA-6 action in these tumor areas may be linked to uncontrolled growth of the tumor cells." (PMID 18405344, 2008). "Both in vivo and in vitro functional experiments confirmed that TGFB2-AS1 critically mediates the tumor-promoting effects of GATA6 in TNBC progression." (PMID 41920409, 2026). "In human PDAC, GATA6 expression correlates with immune cell infiltration, and spatial analysis reveals interaction between GATA6+ tumor cells and CD8+ T cells." (PMID 41651844, 2026). "In pancreatic carcinoma, GATA6 contributes to tumor growth by influencing the Wnt signaling pathway." (PMID 40699746, 2025). "GATA6, for example, has been shown to correlate positively with classical phenotype markers and negatively with basal-like markers in treatment-naive tumor." (PMID 40563550, 2025). "We found that tumor size in mice injected with GATA6- or TET1-depleted CAFs were ~20% smaller than those in the control group (Mice transplanted with scramble siRNA-transfected CAFs) (P < 0.05)." (PMID 40216762, 2025). "Prominently, elevated levels of a variety of transcription factors linked with tumor progression, such as EGFR, FOXM1, STAT3, FGFR1, and GATA6, were identified in the high PANO subtype." (PMID 40918470, 2025). "Knockdown of GATA6 or TET1 attenuated CAF-mediated tumor growth in vivo, underscoring their potential as therapeutic targets." (PMID 40216762, 2025). "HMGA2 expression was significantly higher in tumor cells located farther from acinar cells, whereas GATA6 expression was elevated in tumor cells in close proximity to acinar cell nests, although effect sizes were limited." (PMID 41006303, 2025). "Some studies have identified GATA6 as an oncogenic driver—for instance, GATA6 amplifications can promote tumor growth and metastasis in upper gastrointestinal cancers." (PMID 40862793, 2025). "In “reactive sub-TMEs,” tumor cells exhibited a more basal-like phenotype, evidenced by differentially expressed low GATA6." (PMID 38733987, 2024). "Conversely, GATA6 plays a tumor-suppressive role in cholangiocarcinoma, promoting epithelial–mesenchymal transition (EMT) and metastasis through the MUC1/β-catenin pathway." (PMID 39456519, 2024). "We selected multiple ROIs per histological area and validated GATA6 IHC by evaluating a GATA6 immunofluorescent marker on separate slides for each tumor." (PMID 38733987, 2024). "Recent studies have identified GATA6 as a transcriptional factor and tumor suppressor in a variety of human cancers, including PDA." (PMID 37692474, 2024). "Our unpublished work demonstrated that GATA6 is a crucial suppressor for the pro-tumor immune microenvironment." (PMID 37692474, 2024). "In this context, GATA6 can exhibit an oncogenic function by influencing cell proliferation while also acting as a tumor suppressor by inhibiting EMT transition in vitro, impeding cell propagation in vivo." (PMID 39456519, 2024). "Collectively, these studies emphasize the intricate and multifaceted involvement of lineage survival factors such as GATA6 in tumor progression, highlighting their stage- and content-specific impact." (PMID 39456519, 2024). "Of these 96 PDAC tumors, 88 had sufficient tumor material for GATA6 IHC and 75 for co-expression with classical/basal-like phenotype markers." (PMID 38733987, 2024). "Our study illustrated that the representative PRAPi drug niraparib, restrained PCa cell proliferation, migration and invasion and delayed tumor growth in mice by regulating the MEG3/miR-181-5p/GATA6 pathway." (PMID 38047026, 2023).
tumor (continued). "While GATA4 expression was reduced during tumor progression, GATA6 expression remained highly conserved, except in lymph node metastases." (PMID 36830789, 2023). "In order to study the changes in the expression of GATA4 and GATA6 during the process of tumor development, their expression was studied in healthy tissue, PanIN, tumor tissue, and metastatic lymph node." (PMID 36830789, 2023). "When the differences of GATA4 and GATA6 were studied in the paired samples of PanIN and tumor tissue, it was observed that the expression of GATA4 was lost in 5 (15%) cases, remained the same in 25 (73%) and increased in 4 (12%)." (PMID 36830789, 2023). "Next, immunohistochemistry assay suggested that niraparib treatment intensified MEG3 and GATA6 expression and decreased miR-181-5p expression in tumor tissues, while MEG3 silencing abolished these effects." (PMID 38047026, 2023). "Recent studies propose a tumor-suppressive role of GATA6 in PDAC mouse models, influencing both differentiation and cancer-related transcriptional programs." (PMID 38002058, 2023). "RT‐PCR revealed a significant correlation between the BCL11B and GATA6 expressions in tumor and non‐tumor tissues, and the IHC analysis supported the results in tumor tissue." (PMID 37293953, 2023). "Conversely, GATA6-low basal-like/squamous subtype tumor organoids grow ex vivo independently of Wnt signaling." (PMID 35536676, 2022). "This randomised clinical trial will evaluate two different chemotherapy regimes in the context of molecular profiling and biomarker validation, notably using GATA6 to discriminate between basal and classical tumours." (PMID 35448180, 2022). "Depletion of Gata6 from K14ΔNLef1 epidermis leads to an increase in tumor incidence and frequency, suggesting that Gata6 functions as tumor suppressor in sebaceous lesions." (PMID 36439142, 2022). "GATA4 and GATA5 tend to mark fully differentiated epithelial cells and confirmed as potential tumor suppressors, while GATA6 expresses in the immature proliferating cells in the intestinal crypts and classified as potential oncogene." (PMID 35488350, 2022). "As expected, we found that the percentage of GATA6+ PRMs markedly decreased at week 3 after MC38 tumor inoculation in mice treated with ODN1585 only or ODN+anti–PD-1 compared with mice that received control isotype antibody and anti–PD-1." (PMID 36278484, 2022). "Flow cytometry revealed that the PKH+ macrophages in the tumor environment were GLPMs although the level of Gata6 was downregulated." (PMID 35906202, 2022). "Critically, a recent study authenticates that lncRNA ZnF503-AS1 recruits transcription factor GATA6 and thus exerts its tumor-suppressive function and lncRNA TUG1 enhances cell growth and apoptosis by epigenetically silencing of transcription factor KLF2." (PMID 34858502, 2021). "The classical subtype was characterised by the expression of the endodermal lineage-specifying transcription factor GATA6, KRAS dependency and better survival outcomes, whereas the QM subtype was associated with a high tumour grade and poor survival." (PMID 33406790, 2021). "Tumours of this subtype have lost the expression of key genes involved in endodermal and pancreatic cell fate determination via DNA methylation, including GATA6 and HNF4A, which can distinguish them from the other molecular subtypes." (PMID 33406790, 2021). "Based on the experimental results, we found that upregulation of LINC00261 has tumor suppressive functions in PC stem cells through a regulatory mechanism that LINC00261 increased expression ITIH5 by recruiting GATA6." (PMID 34446696, 2021). "Our study investigates the relevance of GATA6 amplification on a large tumor collective, which includes primary resected tumors and the clinically relevant group of neoadjuvant treated EACs." (PMID 33300112, 2021). "All available PDOs with the corresponding tumor tissue were evaluated for GATA6 and Ki-67 expression by immunohistochemistry." (PMID 34064221, 2021).